COL3A1 (collagen type III alpha 1 chain)
Diseases named in the same sentence as COL3A1 in open-access papers (continued):
Sharing a sentence is not in itself a finding about the gene and the disease.
ovarian carcinoma (continued). "Similar to the mesenchymal subtype from the original TCGA study of ovarian cancer, S‐ECM shows upregulation of genes such as COL5A2, COL1A1, COL3A1, THBS2, COL11A1, COL6A3, and MMP2 that are involved in epithelial‐to‐mesenchymal transformation (EMT) processes, metastasis, and chemoresistance." (PMID 36637997, 2023). "In addition, transcriptomic analysis of the TCGA-ovarian cancer dataset revealed a positive correlation of ITGA2 expression to COL1A2, COL3A1, and COL5A1 involved in focal adhesion pathway." (PMID 33026975, 2020). "Survival analysis revealed that the RNA expression levels for the COL3A1, GPR158 and PITHD1 genes were significantly correlated with that shown on the protein expression levels, proposing them as prognostic factors for ovarian carcinoma (COL3A1) and in MC (GPR158) and CCC histotypes (PITHD1)." (PMID 31533654, 2019). "Since we previously observed that COL3A1, LUM and MYOT (under review) are secreted to cell culture media in drug resistant ovarian cancer cell lines, we were interested whether MGP can also be present in the culture medium." (PMID 30257426, 2018). "It is also noticed that the origins of high COL1A1, COL1A2, and COL3A1 expression positively correlate with fibroblast-specific markers (FAP) and smooth muscle actin (ACTA2), whereas COL4A1, COL4A2, and COL18A1 seem to be predominantly expressed in ovarian cancer cells." (PMID 33026975, 2020). "Interestingly, according to the expression profiling based on the parabiosis model of ovarian cancer hematogenous metastasis, four genes (POSTN, LUM, COL3A1, COL5A2) of the LMGS were shown to be significantly up-regulated in the omental metastases generated through a hematogenous route." (PMID 31888563, 2019). "The immunohistochemical analysis of COL1A2, COL3A1, and COL21A1 revealed that regardless of the type of analyzed ovarian cancer subtype the expression of those proteins was present not only in the ECM surrounding the tumor (what was expected) but also in cancer cells." (PMID 30583585, 2018).
fibrosis (20 papers, 2013 to 2025). the formation of excess fibrous connective tissue in an organ or tissue in a reparative or reactive process. "Next, we found that in the CCl4-induced fibrosis model, the mRNA expression of Col1a1, Col3a1, and α-SMA increase, while these elevations were abrogated in the MlkliΔEC/iΔEC group, as shown by RT-qPCR." (PMID 37511074, 2023). "Hepatic CCN2 expression was significantly induced in NASH patients with F3–F4 fibrosis and was positively correlated with hepatic Col1A1, Col1A2, Col3A1, or αSMA expression." (PMID 37629004, 2023). "Consistent with the development of pathological LVH, TAC was associated with increased cardiac fibrosis (P < 0.001) and enhanced collagen III (Col3a1) expression (P < 0.001) in both WTLs and Piezo1P1-tdT/P1-tdT mice." (PMID 39195867, 2022). "qPCR analysis showed a decrease in highly upregulated gene levels associated with HSC activation, namely Acta2, Col1a2, Col3a1, TIMP-1, TGF-b, and PDGFR-b, in the neratinib-treated group compared to that in the vehicle-treated fibrosis group." (PMID 32901093, 2020). "Finally, the disease gene-association analysis on the DEGs without the respiratory tract disease filter showed that six DEGs (namely, ACTG2, AGER, COL1A1, COL3A1, IGF1, and SPP1) were associated with fibrosis." (PMID 39944354, 2024). "Meanwhile, the cardiac fibrosis is also promoted with the featured phenotype of interstitial and perivascular fibrosis, signatured with upregulated Col1a1, Col3a1 and Tgfb expression, along with a significant increase of MMP-2 and surge upregulated active-MMP-9." (PMID 36834504, 2023). "Interestingly, the fibrosis markers (Vim, Acta2 and Postn) and ECM genes (Col1a2, Col3a1 and Fn1) were upregulated in YB-1 knockdown mice, demonstrating that knockdown of YB-1 promotes cardiac fibrosis and ECM remodeling." (PMID 31588235, 2019). "The extent of liver granuloma and fibrosis was evaluated by monitoring the liver aspect, collagen deposition (Sirius red staining), and HSCs activation [high RNA and protein expression levels of Acta2 (which encodes α-SMA), Col1a1, and Col3a1]." (PMID 29321784, 2017). "We overexpressed miR-486-5p in MRC-5 cells, a cell line commonly used in fibrosis research, and observed a decrease in the expression of fibrosis genes, including Fn, α-SMA, vimentin, COL1A1, and COL3A1." (PMID 40692863, 2025). "In our findings, the suppression of ALKBH5 promoted the expression of COL3A1, COL1A1 and ELN, and these increased ECM components were subsequently secreted and deposited within the dermis, culminating in dermal fibrosis and scar hyperplasia." (PMID 39233335, 2024). "Fibrosis is characterized by expansion and remodeling of the extracellular matrix (ECM) as well as the upregulated expression of type I collagen alpha 1 (COL1A1), type III collagen alpha 1 (COL3A1), etc.." (PMID 38710658, 2024).
cardiac hypertrophy (19 papers, 2009 to 2025). "The mRNA levels of genes related to cardiac hypertrophy (Anp, Bnp, and Myh7) and fibrosis (Col1a1, Col3a1, and Ctgf) were upregulated in AAV‐TEAD1‐K177R mice." (PMID 38225750, 2024). "In HFD + L-NAME mice, the expression of HDAC6 protein was also increased, correlated with the upregulation of Nppb and Col3a1, and severity of diastolic dysfunction [based on the early diastolic velocity ratio (E/e’)] and cardiac hypertrophy (based on LVPWd)." (PMID 38409164, 2024). "Markers for pathologic cardiac hypertrophy (Anp), fibrosis (Col1a1, Col3a1, and Galectin-3), and inflammation (Cox2 and Tnf-α) were also assessed." (PMID 36986490, 2023). "According to previous studies, collagen fibers COL1A1 and COL3A1 play an important role in cardiac hypertrophy." (PMID 36091816, 2022). "The immune-function related gene Col3a1 was down-regulated in response to exercise in mice (1.6, 3.1-fold) and rats (1.8-fold) but up-regulated in most pathological cardiac hypertrophy models." (PMID 32848751, 2020). "There are total 59 genetic variation in the study of physiological cardiac hypertrophy in swimming mice or treadmill rats, only two genes (Cd74 and Col3a1) are changed in both mice and rat models." (PMID 32848751, 2020). "This also applies for markers of cardiac hypertrophy (ANF, BNP, Col3a1), frequently used as indicators of hypertrophy in cardiac-specific conditional knockout mice." (PMID 23929940, 2013). "TAC‐induced myocardial hypertrophy and cardiac fibrosis were also attenuated upon HIPK1 knockdown, accompanied with reduced expression of pathological hypertrophy marker genes (ANP, BNP, and β‐MHC) and fibrosis‐associated genes (Col1a1, Col3a1, and CTGF)." (PMID 37098980, 2023). "Col1a1 and col3a1 are closely related to the formation of myocardial hypertrophy." (PMID 36046382, 2022). "The increased ratio of Col1a1 to Col3a1 at the protein level could be a factor in the stiffness and resistance to stretch in both in HFpEF and HFrEF in different heart failure and hypertrophy forms." (PMID 31380269, 2019). "At protein level, H3L overexpression upregulated expression levels of cardiac hypertrophy marker (NPPB) and cardiac fibrosis markers (COL1A1 and COL3A1)." (PMID 39168969, 2024). "Accordingly, analysis of gene expression demonstrated upregulation of mRNA levels related to myocardial hypertrophy (ANP and β-MHC) and fibrosis (Col3a1) in the hearts of TAC mice compared to the sham group." (PMID 38104081, 2023). "Further supporting this, the observed reduction in HFD-induced fibrotic gene expression (Col1a1, Col3a1, Mmp9) by SAAR suggests a protective effect against the abnormal remodeling of the extracellular matrix that normally accompanies pathological cardiac hypertrophy." (PMID 39770968, 2024). "Furthermore, at the protein level, the overexpression of H3L substantially increased the expression levels of cardiac hypertrophy markers (NPPB) and cardiac fibrosis markers (COL1A1 and COL3A1)." (PMID 39168969, 2024). "Next, we measured genes typically upregulated in pathological cardiac hypertrophy: genes regulating collagen synthesis (Col1a1, Col3a1, Col8a1, and Ccl2) were not altered by diet." (PMID 35736495, 2022).
glioma (19 papers, 2016 to 2025). A benign or malignant brain and spinal cord tumor that arises from glial cells (astrocytes, oligodendrocytes, ependymal cells). "In lower-grade glioma, COL3A1, COL4A1, and COL5A1 are associated with patient prognosis and tumor progression." (PMID 34691289, 2021). "COL3A1 can regulate the immunosuppressive microenvironment in glioma and participate in the EMT process." (PMID 41465316, 2025). "They reported COL3A1 upregulation in glioma cells and showed that COL3AI silencing in vitro was sufficient to inhibit glioma cell proliferation and migration." (PMID 38969910, 2024). "Our Kaplan–Meier analysis demonstrated that high expression of COL1A1, COL1A2, COL3A1, COL5A1, COL8A1, ELN, FN1 resulted in lower OS in all grade glioma patients, in turn causing poor prognosis." (PMID 36106447, 2022). "In a recent study, the collagen molecules COL4A1 and COL3A1 were proved to be essential for the development of glioma." (PMID 34034744, 2021). "Based on the GEPIA database, the expression of COL3A1 in glioma (LGG and GBM) was higher than normal samples." (PMID 34034744, 2021). "To further explore the function of collagen genes in promoting glioma progression, we used rarely studied COL3A1 as a further research object." (PMID 34034744, 2021). "We determined that RRM2 and COL3A1 were up-regulated and directly correlated with glioma grade, while SH3GL2 and SNAP91 were down-regulated in GBM and inversely correlated with glioma grade." (PMID 27655637, 2016). "Knockdown of COL3A1 significantly inhibits the migration and invasion ability of glioma cells." (PMID 41465316, 2025). "Interestingly, miR128-3p was able to modulate the expression of COL3AI in glioma, and the expression of miR128-3p and COL3A1 are inversely correlated." (PMID 38969910, 2024). "RT‐qPCR was performed to detect the expression of BIRC5 and COL3A1 in glioma tissues and cells." (PMID 37340587, 2023). "In glioma, knockdown of COL3A1 could significantly inhibit the migration, invasion, and epithelial-mesenchymal transition (EMT) processes of tumor cells in vitro." (PMID 37415178, 2023). "COL3A1 has been shown to be associated with poor prognosis and drug resistance in GBM patients, so we mainly focused on whether MFAP4 plays an important role in the development of gliomas." (PMID 40061958, 2025). "ALDH16A1 and COL3A1 play important roles in regulating the immunosuppressive microenvironment, tumor cell proliferation and EMT process in glioma." (PMID 40299526, 2025). "Higher expression of COL1A1, COL1A2, COL3A1, COL4A1, COL4A2, and COL5A2 was negatively correlated with the prognosis of glioma patients." (PMID 38969910, 2024). "CENPA, COL3A1, GRP65, SRPX2 and GPX8 were upregulated in glioma, while remaining genes were downregulated." (PMID 39620895, 2024). "According to TCGA dataset, EMT markers have been reported to be strongly related with collagen genes in glioma and COL3A1 knockdown inhibits EMT, cell migration, invasion in glioma cell." (PMID 37414855, 2023). "Then, six collagen genes (COL1A1, COL1A2, COL3A1, COL4A1, COL4A2, and COL5A2) were selected for further validation in Oncomine, TCGA (The Cancer Genome Atlas), and CGGA (Chinese Glioma Genome Atlas) database." (PMID 34034744, 2021). "On the CGGA website (mRNAseq_325), collagen genes (COL1A1, COL1A2, COL3A1, COL4A1, COL4A2, and COL5A2) in WHO grades II, III, and IV glioma samples were analyzed to explore the expression levels of these genes." (PMID 34034744, 2021). "The results showed that the knockdown of COL3A1 decreased the migration, invasion, and EMT process of glioma cells." (PMID 34034744, 2021). "We determined that RRM2 and COL3A1 were increased and directly correlated with glioma grade, while SH3GL2 and SNAP91 were decreased in GBM and inversely correlated with glioma grade." (PMID 27655637, 2016).
glioma (continued). "In particular, several collagen-related genes (e.g., COL1A1, COL3A1, COL5A1) were significantly upregulated, suggesting increased extracellular matrix deposition and the establishment of an immunosuppressive microenvironment in Grade 4 gliomas." (PMID 41432874, 2025). "In detail, COL1A1, COL1A2, COL3A1, COL4A1, and COL4A2 positively correlated with the infiltration of B cells, CD8+T cells, CD4+T cells, macrophages, neutrophils, and dendritic cells in low-grade glioma." (PMID 38969910, 2024). "Accordingly, the knockdown of COL3A1 by using small interfering RNA (siRNA) in SHG44 and A172 cells suppressed migration, invasion, and epithelial-mesenchymal transition (EMT) process in glioma cells." (PMID 38969910, 2024). "It was found that BIRC5 had an abnormally high expression in glioma tissues and cells, while no significant change was observed in the expression of COL3A1." (PMID 37340587, 2023). "Compared with normal tissues, Cd4, Spp1 and Col3a1 expression were significantly increased in glioma tissues (Cd4, p < 0.05; Spp1, p < 0.05; Col3a1, p < 0.05), but their expression levels were not correlated with overall survival." (PMID 36147842, 2022). "In conclusion, the collagen genes (COL1A1, COL1A2, COL3A1, COL4A1, COL4A2, and COL5A2) could regulate the immunosuppressive microenvironment and be involved in the EMT process of glioma." (PMID 34034744, 2021). "Finally, taking COL3A1 as a further research object, the result showed that knockdown COL3A1 could significantly inhibit the migration, invasion, and EMT process of glioma cells in vitro." (PMID 34034744, 2021). "Importantly, we identified that 6 collagen genes (COL1A1, COL1A2, COL3A1, COL4A1, COL4A2, and COL5A2) could regulate the immunosuppressive microenvironment of glioma." (PMID 34034744, 2021). "We found that expression of up-regulated DEGs RRM2 and COL3A1 (>2-fold up-regulated as determined by the gene expression profile) was significantly higher in malignant gliomas compared to lower grade gliomas and non-tumor brain tissue and directly correlated with glioma grade." (PMID 27655637, 2016).
gastric cancer (18 papers, 2012 to 2025). A primary or metastatic malignant neoplasm involving the stomach. "For example, COL3A1 encoding Type III collagen is one of the upregulated hub DEGs in gastric cancer and predicts poor prognosis in patients ​based on the data downloaded from the GEO database." (PMID 34900998, 2021). "COL3A1 has been associated with gastric cancer diagnosis, prognosis and therapy." (PMID 34062972, 2021). "We identified several genes, including FN1, COL1A2, THBS2, COL3A1, COL5A1, and BGN, which appear to be associated with poorer outcomes for stomach cancer patients." (PMID 38610959, 2024). "High expression of COL1A1, COL3A1, COL5A1, FN1, and SPARC was significantly associated with poor survival in gastric cancer patients (p < 0.05)." (PMID 35739492, 2022). "Col1a1, fga, fgg, f2r, col3a1, and col1a2 are the important genes of this pathway, which are upregulated in gastric cancer." (PMID 35650297, 2022). "COL3A1 has been found to be over-expressed in a range of cancers, such as bladder cancer, glioblastoma, and gastric cancer, in addition to its normal expression in connective tissues." (PMID 36059672, 2022). "Except for normal localization in connective tissues, COL3A1 was also found to be highly expressed in various cancers including bladder cancer, glioblastoma, and gastric cancer." (PMID 32766145, 2020). "In summary, we uncovered the prognostic value of COL3A1/FBN1/COL5A2/SPARC-mir-29a-3p-H19 ceRNA network in gastric cancer." (PMID 32742441, 2020). "In addition, we identified three key mRNAs (CD93, COL3A1 and COL4A1) associated with gastric cancer peritoneal metastasis through WGCNA analysis and clinical specimen validation." (PMID 36690975, 2023). "Another in‐silico‐based study that analyzed multiple publicly available datasets identified collagen genes COL1A1, COL1A2, COL3A1, and COL5A1 as key CAF markers in gastric cancers." (PMID 39245631, 2025). "In this study, we performed whole-transcriptome sequencing on tissue samples of gastric cancer peritoneal metastasis, and identified GCPM-related lncRNAs (lnc-RFNG-1 and lnc-TRIM28-14) and mRNAs (CD93, COL3A1, and COL4A1)." (PMID 36690975, 2023). "Similar results were also found in gastric cancer, in which the upregulated genes were COL1A2 and COL6A3 or COL6A3, COL3A1, and COL1A1." (PMID 38069077, 2023). "We identified ECM components COL1A1, COL1A2, COL3A1, COL5A1, FN1, and SPARC as the pivotal CAF markers in gastric cancer, which were separately reported as biomarkers of gastric cancer in different studies." (PMID 35739492, 2022). "Our study revealed the COL1A1, COL1A2, COL3A1, COL5A1, FN1, and SPARC as the key CAF markers in gastric cancer." (PMID 35739492, 2022). "In this study, we identified the six key CAF markers namely COL1A1, COL1A2, COL3A1, COL5A1, FN1, and SPARC in gastric cancer that can be used as predictors of CAF infiltration and prognostic biomarkers in gastric cancer." (PMID 35739492, 2022). "Eight out of 38 upregulated genes in gastric cancer (ASPN, COL1A1, COL1A2, COL3A1, COL5A1, FAP, FN1, and SPARC) overlapped with the CAF markers list (circos plot on the left)." (PMID 35739492, 2022). "As members of the collagen family, both COL3A1 and COL5A2 had significant value in the prognosis of gastric cancer." (PMID 33828526, 2021). "Hence the module analysis strengthened the connection of the six CAF markers: COL1A1, COL1A2, COL3A1, COL5A1, FN1 and, SPARC, with the 3 KEGG pathways: ECM-receptor interaction, focal adhesion and, PI3K-Akt signaling pathway in gastric cancer." (PMID 35739492, 2022). "The results showed that 8 up-regulated genes (FN1, COL3A1, FBN1, BGN, COL5A2, THBS2, COL5A1 and SPARC) and 1 down-regulated gene (ATP4A) may be the central genes in gastric cancer." (PMID 32742441, 2020).